HMGB1 (high mobility group box 1)
Diseases named in the same sentence as HMGB1 in open-access papers (continued):
Sharing a sentence is not in itself a finding about the gene and the disease.
COVID-19 (continued). "HMGB1, NLRP3 and IL-6 levels were positively correlated with headache in patients with COVID-19." (PMID 37940864, 2023). "HMGB1 and RAGE are overexpressed in COVID-19 patients and correlated with COVID-19 severity." (PMID 37357527, 2023). "SARS-CoV-2 induces an increase in COX-2, HMGB1, RAGE, and GFAP levels in severe COVID-19 cases." (PMID 37357527, 2023). "showing that severe COVID-19 patients (N = 11) had significantly higher levels of HMGB1 than non-severe COVID-19 patients (N = 29)." (PMID 35401579, 2022). "HMGB1 levels in patients with mild COVID-19 and ARDS patients with and without COVID-19 were significantly higher compared with those of healthy individuals (+317%, p = 0.002), but they were not different between COVID-19 and non-COVID-19 ARDS." (PMID 36251689, 2022). "Our data do not permit differentiation with regard to disease severity, as HMGB1 levels are not significantly different in COVID-19 patients with mild courses or with ARDS in the present study." (PMID 36251689, 2022). "Since COVID-19 and MIS-C are both characterized by the severe inflammatory immune response, HMGB1 may represent an alarm signal, indicating an increase in pro-inflammatory triggers." (PMID 35558368, 2022). "Besides activation of the NLRP3 inflammasome and HMGB1, hypoxia-inducible factor-1α (HIF-1α) signaling pathway is also elevated in elderly patients with COVID-19." (PMID 35356515, 2022). "Other groups have shown that HMGB1 can be drastically increased in severe COVID-19 courses compared to mild courses, but our study was not powered for that scope." (PMID 36251689, 2022). "It remains to be explored whether RAGE directly binds C1q or forms C1q complexes with SARS-CoV-2, HMGB1, or binds additional receptors/ligands to promote kidney injury in CKD or COVID-19." (PMID 36017003, 2022). "Further study of these mechanisms and drugs that target RAGE-mediated endocytosis of HMGB1 and its binding partners (e.g., C1q) may offer insight into approaches to regulating inflammatory responses in CKD and COVID-19." (PMID 36017003, 2022). "In the context of COVID-19 immunopathogenesis, excessive amounts of necrotic cells may lead to high levels of circulating DAMP, such as HMGB1 and lactate dehydrogenase (LDH), both of which correlate with disease severity." (PMID 35666101, 2022). "However, increased levels of TLR2 with either TLR1 or TLR6 DAMPs, including beta-defensin-3, named TLR1/2, and the high-mobility group box-1 (HMGB1), named TLR1/2/6, were recorded in peripheral blood mononuclear cells and serum obtained from COVID-19 patients." (PMID 34770863, 2021). "COVID-19 patients with headache had significantly higher serum levels of HMGB1, NLRP3, ACE2, and IL-6 than COVID-19 patients without headache, whereas CGRP and IL-10 levels were similar." (PMID 34794375, 2021). "Elevated HMGB1, NLRP3 and IL-6 levels could be discriminative markers for COVID-19 headache and may have implications for prevention and also for other secondary headaches related to other systemic viral infections." (PMID 34384355, 2021). "In addition, in severe COVID-19, the levels of circulating mitochondrial DNA, S100A8/A9, and high mobility group box 1 were also significantly increased and were correlated with inferior clinical outcomes." (PMID 34817280, 2021). "The present study aimed to investigate whether serum levels of NLRP3, HMGB1, IL-6, IL-10, angiotensin II and ACE2 were different in COVID-19 patients with headache." (PMID 34384355, 2021). "In conclusion, plasma HMGB1 and IL6 at ICU admission may serve as prognostic biomarkers in critically ill COVID-19 patients." (PMID 33939645, 2021). "COVID-19 patients suffered from headache had significantly higher serum levels of HMGB1, NLRP3, ACE2, and IL-6 than COVID-19 patients without headache, whereas CGRP and IL-10 levels were similar in the groups." (PMID 34384355, 2021).
COVID-19 (continued). "Based on our unpublished results we suspect that some standardized HMGB1 ELISAs do not perform accurately with COVID-19 plasma samples and fail to remove complex-bound molecules efficiently from HMGB1, which produces confounding results." (PMID 34943830, 2021). "Indeed, HMGB1-RAGE/TLR4 signaling is believed to mediate endothelial activation and dysfunction in COVID-19 conditions." (PMID 34204735, 2021). "We examined the serum HMGB1 levels of 11 severe and 29 non-severe COVID-19 patients following admission to Xiangya Hospital." (PMID 33313438, 2020). "Another important immunomodulator, high mobility group box 1 protein (HMGB1), could be a contributing factor for sex-specific severity and mortality from COVID-19." (PMID 32948238, 2020). "A distinct immune response is noted between COVID-19 and MIS-C, characterized by a persistent elevation in pro-inflammatory cytokines such as IL-1β, IL-2, IL-6, IFN-α, IL-10, IL-17, granulocyte-macrophage colony-stimulating factor (GM-CSF), and high-mobility group box 1 (HMGB1) among MIS-C patients." (PMID 39931580, 2024). "The fact that all of these COVID-19 subjects survived without experiencing severe complications speaks to the HMGB1 levels most likely reflecting the state of the human body in which it is possible to regulate the immune response with standard medical treatments." (PMID 37685970, 2023). "However, conversely to our result, elevated HMGB1 levels did not statistically differ in patients with COVID-19 hospitalized in the general ward with respect to healthy controls." (PMID 35558368, 2022). "Higher circulating DAMPs (e.g., ds-DNA, HMGB1), and endothelial proteins such as E-selectin, PECAM-1, or ICAM-1 provide a mechanistic link for the prothrombotic state and hepatic portal thrombosis, pulmonary thrombosis induced by LA, which is similar to COVID-19 autopsies." (PMID 35502320, 2022). "The association between HMGB1 levels and the expression of the ACE2 receptor in patients with COVID-19 has not been studied yet, so in future studies, it would be interesting to evaluate their possible correlation, as a mechanism that can modulate the entry of the virus into the respiratory cell." (PMID 35558368, 2022). "In summary the study showed that plasma concentrations of HMGB1 and IL-6 assessed at ICU admission could accurately identify COVID-19 patients with a fatal outcome of the disease, with a predictive precision similar to or better than the SOFA or the COVID-GRAM risk scores." (PMID 33939645, 2021). "However, elevated levels of TLR1/2/6 DAMPs, including beta-defensin-3 (identified by TLR1/2) and high-mobility group box-1 (HMGB1) (identified by TLR1/2/6), have been reported in peripheral blood mononuclear cells and serum collected from COVID-19 patients, respectively." (PMID 33498183, 2021). "Although the current preliminary in vitro studies indicate that HMGB1 has a potential role in COVID-19, novel animal models of SARS-CoV-2 infection will undoubtedly be of great value for further evaluation of the use of HMGB1 inhibitors in the treatment of COVID-19." (PMID 33313438, 2020). "For instance, high mobility group box 1 (HMGB1), which is actively secreted by necrotic cells in response to inflammatory signaling, may contribute to the hyper-inflammatory response seen in COVID-19, leading to complications such as acute respiratory distress syndrome (ARDS) and thrombosis." (PMID 39628664, 2024). "However, the possible roles of HMGB1 and various other cytokines in the pathogenesis of lethal infections such as COVID-19 remain controversial, because there is still a lack of clear association between many cytokine biomarkers and the severity of viral infections." (PMID 34571869, 2021). "We were unable to find similar studies on the role of HMGB2; however, due to the high structural homology of HMGB1 and HMGB2 proteins, the possible role of the latter one in the course/development of COVID-19 cannot be completely ruled out." (PMID 37176041, 2023).
COVID-19 (continued). "A retrospective study, including 121 COVID-19 patients, shows that circulating HMGB1 and S100A8/A9 levels were significantly elevated in ICU-admitted COVID-19 patients (N = 40) compared to non-ICU COVID-19 patients (N = 81)." (PMID 35401579, 2022). "HMGB1 levels between ARDS with and without COVID-19 were not significantly different (p = 0.25), with a median of 19.6 μg/L (IQR, 10.0 to 30.3) and 33.6 μg/L (IQR, 23.3 to 62.4), respectively." (PMID 36251689, 2022). "Compared to COVID − 19 patients without headache, serum levels of HMGB1, NLRP3, IL-6, angiotensin II, and ACE2 were significantly higher in COVID-19 patients with severe headache." (PMID 34384355, 2021). "Plasma levels of HMGB-1 in COVID-19 patients admitted to the ICU were significantly elevated in comparison to healthy subjects and non-ICU COVID-19 patients." (PMID 34566657, 2021). "HMGB1 is enhanced in mild COVID-19 and in ARDS with and without COVID-19, warranting evaluation of HMGB1 as a potential treatment target and glycyrrhizin, which is an active component of liquorice root extract, as a potential treatment in COVID-19 and non-COVID-19 respiratory disease." (PMID 36251689, 2022). "The HMGB1 was not discussed because it was only mentioned 111 times in the entire CORD-19v47 dataset, and only 8 times in the 3,000 articles after filtering the articles for glucose in COVID-19." (PMID 34395368, 2021). "Although there is no application of alarmin blockade in COVID-19 and comorbidities, previous studies have suggested the therapeutic potential of neutralizing antibodies against S100A8/A9, HMGB1, or histones for the inhibition of pulmonary fibrosis and sepsis-associated ALI/ARDS." (PMID 34682694, 2021).
ischemia (115 papers, 2008 to 2026). A hypoperfusion of the BLOOD through an organ or tissue caused by a PATHOLOGIC CONSTRICTION or obstruction of its BLOOD VESSELS, or an absence of BLOOD CIRCULATION. "The association of HMGB1 with inflammation has been well established, specifically in in vivo mice models and humans suffering from trauma, ischemia, and inflammatory diseases." (PMID 36829889, 2023). "Cell injury, necrosis, or activation caused by certain pathological conditions such as ischemia result in the transfer of HMGB1 from the nucleus to the cytoplasm or extracellular space, due to the separation of HMGB1 from the damaged DNA." (PMID 33384585, 2020). "Increased expression of HMGB1 in the blood vessels of the lung is known to cause pulmonary artery hypertension and has a role in ischemia induced blood-brain barrier disruption." (PMID 30728013, 2019). "As a late modulator of inflammation, HMGB1 functions as a damage-associated molecular pattern in the sterile inflammation model by amplifying hepatic ischemia/reperfusion (I/R) and acetaminophen-induced liver necrotic injury." (PMID 29568761, 2018). "Furthermore, HMGB1 acts on target receptors on endothelial progenitor cells (EPCs) to promote peri-infarct angiogenesis, associated with ischemia/reperfusion-induced hemorrhagic transformation(HT)." (PMID 38740617, 2025). "Intravenous injection of anti-HMGB1 monoclonal antibody significantly protected rats from ischemia-induced blood–brain barrier disruption, which was associated with inhibiting the expression of proinflammatory factors like iNOS, TNF-α and MMP9 and microglial cell activation." (PMID 38740617, 2025). "Additionally, HMGB1 has been shown to mediate neutrophil formation of extracellular traps, thereby worsening acute lung injury caused by intestinal ischemia-reperfusion." (PMID 39512354, 2024). "This might indicate that the cause of increased HMGB1 includes other factors (whole-body ischemia including the brain) in PCAS." (PMID 28950909, 2017). "Interestingly, while all animals in our current study demonstrated loss of nuclear HMGB1 in the setting of ischemia 4–24 h after FAL, only MyD88 KO mice and TRIF KO mice had detectable serum HMGB1 levels at these time points." (PMID 24844636, 2014). "All these results supported the hypothesis that the HMGB1 release from various immune cells, including astrocytes, is critical for affecting the nerves regeneration of the brain–immune interaction and causing glutamate-induced neurotoxicity after ischemia." (PMID 33287126, 2020). "The role of HMGB1 extends to influencing the pathogenesis of ischemia by polarizing various subtypes of immune and glial cells." (PMID 38740617, 2025). "Among them, as a highly conserved nuclear protein, HMGB1 can be translocated into the cytoplasm and subsequently released into the extracellular space during ischemia and hypoxia, and it plays a pivotal part in the onset of reperfusion injury." (PMID 41378869, 2025). "HMGB1 plays a crucial role in T cell infiltration and proliferation, and the HMGB1 inhibitor glycyrrhizin prevents ischemia and reduces infarct size in part by inhibiting the infiltration and proliferation of T cells and their subtypes into the ischemic brain." (PMID 38740617, 2025). "Modulation or inhibition of HMGB1 release significantly reduces brain injury and improves neurological outcomes in various disease models, including ischemia, hemorrhage, trauma, epilepsy, and AD." (PMID 40877572, 2025). "Prior investigations revealed that TLR4, HMGB1 and NF‐κB are essential proinflammatory modulators of ischemia‐induced brain injury." (PMID 37132060, 2023). "Several studies have explored the role of HMGB1/TLR4 pathway intensification in hepatic ischemia-induced injury." (PMID 36294936, 2022). "Cardiac perfusate isolated following ischemia had significantly reduced cardiac troponin T, HMGB1, cell-free DNA, and interferon α and β levels after NC." (PMID 35837603, 2022).
ischemia (continued). "As neuron cell membranes are destroyed, HMGB1 loosely bound to chromosomes is passively released into the extracellular space within 2–4 h after ischemia–reperfusion." (PMID 36421725, 2022). "Accordingly, serum HMGB1 levels were significantly elevated in mice with hindlimb I/R compared with normal mice or mice with hindlimb ischemia (P < 0.05)." (PMID 34381442, 2021). "On the one hand, hepatocyte-specific HMGB1 knockout mice suffer from increased mitochondrial damage and cell death during liver ischemia/reperfusion." (PMID 34366845, 2021). "In mice pretreated with 40 mg/kg osthole, HMGB1 release was significantly inhibited after ischemia injury, and the nucleoplasmic migration of HMGB1 in epithelial cells was reduced." (PMID 35002751, 2021). "The morphological changes in BBB structures were consistent with the results of BBB permeability measurement and upregulation of aquaporin-4 on the astrocytic endfeet around capillaries after ischemia, which were also suppressed by anti-HMGB1 mAb treatment." (PMID 33321691, 2020). "Intravenous injection of anti-HMGB1 mAb significantly protected against BBB disruption induced by ischemia and hemorrhage in rats while simultaneously inhibiting the expression of inflammation-related molecules and the activation of microglia." (PMID 33321691, 2020). "It was also reported that an increase in HMGB1 protein was observed in the area of the penumbra after ischemia or hemorrhage, suggesting that HMGB1 dynamics in such areas differ according to the extent of the neural lesion." (PMID 33321691, 2020). "As in the case of brain injury induced by ischemia, anti-HMGB1 mAb inhibited the activation of glia cells and the expression of proinflammatory cytokines, as well as inflammation-related factors." (PMID 33321691, 2020). "Treatment with PROG reduced peripheral and hippocampal HMGB1 release induced by global ischemia, which was worsened by comorbid stress." (PMID 32466385, 2020). "At 7 days post-ischemia, serum and hippocampal HMGB1 levels were equally elevated in Stress+Sham and ISCH groups compared to Sham controls." (PMID 32466385, 2020). "We can now confirm previous studies showing that the alarmin HMGB1 is released in response to stress and ischemia." (PMID 32466385, 2020). "A role for the higher production of reactive oxygen species in the increased HMGB-1 levels was suggested, due to vascular ischemia and reperfusion injury after Raynaud’s phenomenon." (PMID 32679721, 2020). "The Stress+ISCH group showed higher serum and hippocampal HMGB1 levels in comparison with unstressed ischemic animals, suggesting a synergistic effect between stress and ischemia on HMGB1 release." (PMID 32466385, 2020). "Myocardial HMGB1 expression increases soon after ischemia and remains high several days after reperfusion." (PMID 30306212, 2019). "The study showed that the HMGB1 inhibitor glycyrrhizin protects against ischemia partly by inhibiting the infiltration of T cells and their subtypes into the ischemic brain." (PMID 31001089, 2019). "Our previous study showed that stimulating the vagal nerve by electroacupuncture in vivo or pretreating neonatal cardiomyocytes with acetylcholine in vitro inhibited ischemia or hypoxia-induced cardiac HMGB1 release through an α7nAchR-dependent mechanism." (PMID 31344138, 2019). "In a hepatic ischemia/reperfusion injury model, enhanced acetylation promoted HMGB1 translocation and release in liver cells." (PMID 31333497, 2019). "HMGB1 is one of the main factors contributing to ischemia–reperfusion injury and is a potential therapeutic target for ischemia." (PMID 29696019, 2018). "Our findings, along with the observation that anti-HMGB1 Ab treatment protects BBB from ischemia-induced disruption in rats, lead us to conclude that HMGB1-mediated complement activation plays an important role in the permeability of BBB." (PMID 29696019, 2018).